MIF (macrophage migration inhibitory factor)
Diseases named in the same sentence as MIF in open-access papers (continued):
Sharing a sentence is not in itself a finding about the gene and the disease.
crescentic glomerulonephritis (8 papers, 2010 to 2025). A histopathologic term for a pattern of diseases characterized by extensive crescent formation in the glomeruli; patients present clinically with rapid deterioration of renal function, and possible progression to end-stage renal failure within weeks or months. "It is well established that macrophages and MIF play a pathogenic role in anti-glomerular basement membrane crescentic glomerulonephritis (anti-GBM CGN)." (PMID 38846956, 2024). "Experimental studies have demonstrated the pathogenic role of MIF in immune-mediated renal injury, crescentic glomerulonephritis, and podocyte injury." (PMID 28813470, 2017). "However, genetic MIF/CD74 deficiency or blocking MIF activity can ameliorate glomerular injury and partially reverse established crescentic glomerulonephritis." (PMID 35360248, 2022). "Further, it could interfere with MIF/CD74 signaling and CD74 deficiency, which can have protective effects against crescentic glomerulonephritis." (PMID 33779731, 2021). "MIF overexpression promotes while MIF targeting protects from experimental glomerular injury and kidney cysts, and interference with MIF/CD74 signaling or CD74 deficiency protected from crescentic glomerulonephritis." (PMID 26441987, 2015). "Evidence to support a critical role of MIF in macrophage-mediated renal injury also comes from the finding that blockade of MIF with a neutralizing MIF antibody is able to prevent or reverse macrophage accumulation and activation in a mouse or rat model of crescentic glomerulonephritis." (PMID 35563296, 2022). "In addition to CD74, the signal transduction of MIF requires the recruitment and activation of CD44, a PEC activation marker, to induce PEC activation and pathological proliferation in crescentic glomerulonephritis." (PMID 35360248, 2022). "Macrophage migration inhibitory factor (MIF), a pleiotropic, proinflammatory cytokine, produced by injured podocytes, is a signaling molecule that mediates pathological PEC proliferation via CD74/CD44, thereby leading to an aggressive and progressive course of crescentic glomerulonephritis." (PMID 35360248, 2022).
emphysema (8 papers, 2015 to 2024). "In addition, both MIF-deficient and CD74-deficient mice were found to develop aged-related emphysema and MIF-deficient mice developed even worse emphysema when exposed to cigarette smoke than MIF-deficient mice exposed to air." (PMID 35091838, 2022). "In addition, mice deficient for MIF were shown to spontaneously develop emphysema, emphasizing the importance of MIF for alveolar repair." (PMID 34098338, 2021). "Further, it was shown that the response to cigarette smoke was age-dependent, while MIF knock-out mice developed spontaneous emphysema and were more prone to cigarette smoke-induced emphysema." (PMID 39337534, 2024). "Another study, conducted in murine models, supported that MIF may contribute to emphysema pathogenesis by maintaining vascular homeostasis under oxidative stress." (PMID 39337534, 2024). "Mice exposed to cigarette smoke for three months had higher MIF levels in bronchoalveolar lavage fluid whereas mice exposed for six months had lower MIF levels compared to nonexposed controls and this coincided with emphysema development." (PMID 35091838, 2022). "Overall, these data indicate that MIF may play a role in driving COPD inflammation and AHR but not emphysema." (PMID 26752192, 2016).
Hepatitis (8 papers, 2009 to 2023). Inflammation of the liver. "MIF manifests its pro-inflammatory nature, showing high expression levels in tissues with chronic inflammation areas, such as hepatitis, gastritis and pancreatic." (PMID 34157052, 2021). "It inhibits the PI3K/Akt/mTOR pathway that is implicated in EAE and MS, and in an effective fashion prevents the development of a MIF-dependent immunoinflammamtory hepatitis in mice." (PMID 31581595, 2019). "From the health to hepatitis, the MIF signaling network and related ligand-receptor interactions, including MIF-(CD74 + CXCR4), MIF-(CD74 + CXCR2), and MIF-(CD74 + CD44) showed a significant effect on macrophage–naïve CD4 + T cell interaction." (PMID 36221095, 2022).
metastatic disease (8 papers, 2014 to 2024). "We further compared the ligand-receptor interactions between endothelial cells and other cells and found that the MIF pathway had a significant effect on immune cells within metastatic tumors, especially monocytes and T cells." (PMID 38951874, 2024). "Tumors can relapse and/or reappear as metastatic disease years after the resection of the primary tumor; our data strongly suggest that MIF also plays a key role in spontaneous lung metastasis of TNBC." (PMID 32943608, 2020). "According to the distinct expression of MIF in primary tumors from metastatic tumors, we classified all samples into two groups." (PMID 26087187, 2015). "While further investigations will help to elucidate these mechanistic details, it is becoming increasingly evident that MIF plays an important regulatory role in governing TAM-dependent tumor initiation, progression, and metastatic disease phenotypes." (PMID 33324425, 2020).
preeclampsia (8 papers, 2012 to 2025). Preeclampsia is a hypertensive disorder of pregnancy that is characterized by new-onset hypertension with proteinuria presenting after 20 weeks of gestation, and depending on mild or severe forms may initially present with severe headache, visual disturbances, and hyperreflexia. "In particular, lower MIF levels in early pregnancy have been associated with recurrent miscarriage, while higher levels in late pregnancy have been correlated with preeclampsia, the main cause of maternal and fetal mortality and morbidity worldwide." (PMID 24737926, 2014). "Previous studies have shown that maternal peripheral serum MIF is associated with preterm delivery and preeclampsia." (PMID 23272137, 2012). "Any variation of MIF, towards either an increase or a decrease in the maternal serum, has been associated with complications in human pregnancy, including miscarriage, preterm labour, and preeclampsia." (PMID 24737926, 2014). "This PE-PDMSCs induced alteration in MIF expression further confirm the contribution of pathological mesenchymal stromal cells to the pathogenesis of preeclampsia." (PMID 23527185, 2013). "Of clinical relevance, we were able to discriminate between placental and maternal preeclampsia on the base of MIF source within fetoplacental tissues." (PMID 22007254, 2012). "MIF maternal serum levels are increased in preeclampsia (PE)." (PMID 22007254, 2012). "Our research showed that SPP1, Annexin, MIF, Visfatin, VEGF, Galectin, PTN, and CCL signalings were significantly inhibited among the three subtypes of macrophages in the preeclampsia group." (PMID 40216654, 2025). "RT-qPCR confirmed aberrant expression of genes involved in inflammation and stress response (TLR4 and TLR9) and also genes involved in host defense (PRDX5, MIF, CD74, NFE2L1, and CSF3R), suggesting that preeclampsia sera suppress the TLR4/9-dependent excess oxidative stress in adipose tissue." (PMID 26089598, 2015).
squamous cell carcinoma (8 papers, 2009 to 2025). A carcinoma arising from squamous epithelial cells. "Some cytokines are strongly implicated in the development of squamous cell carcinoma (SCC) such as the Macrophage migration inhibitory factor (MIF)." (PMID 37485818, 2023). "Compared with adenocarcinoma, squamous cell carcinoma showed strong communications with endothelial by the MIF/TNFRSF10D, EGFR/GRN, EGFR/HBEGF, and EPHB2/EFNB2 interactions." (PMID 34185421, 2021). "In particular, MIF activation confers chemotherapeutic resistance, and its inhibition through MIF inhibitor 4‐IPP reverses chemotherapy resistance in SCCVII squamous carcinoma cells." (PMID 29896883, 2018). "Five additional samples of adenocarcinoma, squamous cell carcinoma and normal lung were evaluated for MIF and PTRF using IHC." (PMID 22461895, 2012). "The same samples used for MS/MS analyses and nine additional samples of adenocarcinoma, squamous cell carcinoma and normal lung were evaluated for MIF and PTRF using western blot." (PMID 22461895, 2012). "Additionally, MIF protein was also increased in the serum from squamous carcinoma mice compared to the serum from normal mice in vivo." (PMID 39891284, 2025). "For the first time, our data from analyses of intercellular interactions and in vitro experiments clearly demonstrated that squamous cell carcinoma cells of the head and neck mediate the transdifferentiation of myeloid cells into CAFs through the secretion of MIF." (PMID 39891284, 2025). "Furthermore, cytoplasmic MIF has also been proposed to have prognostic value in squamous cell carcinoma patients." (PMID 38612413, 2024).
uveal melanoma (8 papers, 2014 to 2025). A melanoma derived from melanocytes of the uveal tract. "Macrophage Migration Inhibitory Factor (MIF) plays a role in the carcinogenesis of many cancer types, including uveal melanoma, and its inhibition can lead to cell migration." (PMID 40016808, 2025). "In uveal melanoma, MIF overexpression suppresses natural killer (NK) cell activity, thus establishing an immunosuppression." (PMID 38732068, 2024). "have reported that uveal melanoma exosomes promote cancer progression by inducing a cancer immunosuppressive microenvironment through macrophage migration inhibitory factor (MIF)." (PMID 36727049, 2022). "They studied the supernatant of primary uveal melanoma tumors and metastases and showed that uveal melanoma metastases produced two-fold more MIF than primary uveal melanoma." (PMID 31013837, 2019). "MIF production was also shown in human uveal melanoma cell lines whereby MIF prevented their lysis by NK cells." (PMID 25168062, 2014). "Moreover, metastatic cell lines produced about twice the amount of functional MIF as compared to primary uveal melanoma cell lines." (PMID 33317028, 2020). "Interestingly, MIF is also produced by uveal melanoma cells, enabling them to suppress NK cell function." (PMID 33317028, 2020). "Subsequent studies found that MIF-dependent NK cell inhibitory functions are not restricted to the aqueous humor and uveal melanoma cells of the eye." (PMID 33324425, 2020).
acute pancreatitis (7 papers, 2010 to 2024). An acute inflammatory process that leads to necrosis of the pancreatic parenchyma. "Inhibition of MIF has led to alleviated damage in pancreatic and renal tissues in a severe acute pancreatitis model through the attenuation of the NLRP3 pathway." (PMID 38585277, 2024). "In our previous study using a mouse model of severe acute pancreatitis, we found that deletion of MIF reduced inflammation." (PMID 36160453, 2022). "Serum macrophage migration inhibitory factor (MIF) was reported to be correlated with severity of acute pancreatitis (AP) based on the 1992 Atlanta classification." (PMID 33482739, 2021). "In addition, MIF inhibitor ISO-1 was reported to protect severe acute pancreatitis by suppressing phosphorylated P38 and nuclear factor-κB (NF-κB) signaling." (PMID 36160453, 2022). "In addition, modulation of MIF may have therapeutic advantages in treating acute lung injury in patients with acute pancreatitis complicated by bacterial infection." (PMID 20169062, 2010). "During the induction of acute pancreatitis mice utilizing LPS, an upregulation of both TLR4 and MIF were observed in the lungs of treated mice." (PMID 38585277, 2024).
atrial fibrillation (7 papers, 2020 to 2025). A disorder characterized by an electrocardiographic finding of a supraventricular arrhythmia characterized by the replacement of consistent P waves by rapid oscillations or fibrillatory waves that vary in size, shape and timing and are accompanied by an irregular ventricular response. "Additional evidence suggests that intraoperative serum MIF levels during myocardial reperfusion are independently associated with a lower risk of post-operative atrial fibrillation." (PMID 36712241, 2022). "A higher circulating level of MIF was reported in patients with atrial fibrillation." (PMID 36712241, 2022). "Macrophage migration inhibitory factor (MIF), a pleiotropic inflammatory cytokine, is highly expressed in patients with atrial fibrillation (AF)." (PMID 36056883, 2023).
autoimmune hepatitis (7 papers, 2018 to 2025). Hepatitis caused by autoantibodies. "MIF is also associated with the disease severity in autoimmune hepatitis and in cholestatic liver disease." (PMID 31370326, 2019). "In autoimmune hepatitis (AIH), serum MIF levels were increased compared to controls and associated with the necessity to receive steroid treatment." (PMID 31370326, 2019). "Interestingly, in autoimmune hepatitis, a chronic liver disease with a known connection to MIF, hepatic production of chemokines are primarily T cell chemotactic factors outside of the IL-8 family." (PMID 33945507, 2021).
cerebral malaria (7 papers, 2009 to 2022). A sequestration of Plasmodium falciparum in the brain, which can cause coma and/or seizures. "A clinical study in India showed that high concentrations of MIF in the plasma are associated with death in cerebral malaria patients." (PMID 22496958, 2012). "In logistic regression on cerebral malaria patients, log MIF levels were found to be significantly associated with fatal outcome (odds ratio 4.0; 95%CI 1.6, 9.8; p = 0.003)." (PMID 19284533, 2009). "Furthermore, additional studies suggest the implication of MIF in the pathogenesis of cerebral malaria, as higher MIF plasma concentrations were found to be associated with higher mortality in patients." (PMID 35464430, 2022). "This study suggests that elevated levels of MIF in the peripheral blood of cerebral malaria patients may be associated with fatal outcomes." (PMID 19284533, 2009). "However, the mechanisms involved in MIF-associated diseases are still incompletely understood and points to the fact that little is known about the role of this factor in cerebral malaria patients." (PMID 19284533, 2009). "Increased MIF expression correlated with death in patients with cerebral malaria as well as the development of placental malaria which is in accord with the role of MIF in the inflammatory clinical sequelae of Plasmodium infection." (PMID 32244916, 2020). "Necropsy studies show a decrease in endothelial cell expression of MIF in brain vessels of cerebral malaria patients when compared to endothelial cells from axillary and chest vessels." (PMID 22496958, 2012). "The current study investigated the role of circulating MIF in the pathogenesis and outcomes of cerebral malaria." (PMID 19284533, 2009). "Few studies in humans indicate that MIF is involved in the pathogenesis of cerebral malaria." (PMID 22496958, 2012). "The role of circulating MIF in the pathogenesis of cerebral malaria (CM) and its outcome has not been investigated." (PMID 19284533, 2009).
Hashimoto thyroiditis (7 papers, 2014 to 2025). An autoimmune disorder caused by the production of autoantibodies against thyroid tissue. "Recent analyses have shown that MIF is not only important in inflammation and infection, but also contributes to the development of Hashimoto’s thyroiditis by influencing the differentiation and development of Th17 lymphocytes." (PMID 38999993, 2024). "In the latest research on the pathogenesis of Hashimoto’s thyroiditis, the influence of MIF on antibodies occurring over the course of the disease has also been demonstrated." (PMID 38999993, 2024). "The other two studies showed that MIF levels are higher in Hashimoto’s disease, and MIF is also involved in the development of autoimmune thyroid disease." (PMID 34575145, 2021). "Previous studies have also shown a significant relationship between MIF in Graves’ disease and Hashimoto’s disease." (PMID 34575145, 2021). "Further investigations are needed to explore the role of MIF in pathogenesis of Hashimoto’s thyroiditis." (PMID 25506398, 2014). "In conclusion, we have shown that MIF increases in overt hypothyroidism due to the Hashimoto’s thyroiditis." (PMID 25506398, 2014). "Since the original role of MIF is linked to the cell mediated immunity-induced tissue destructive lesions that has been accepted to play a role in Hashimoto’s thyroiditis, another interest will be addressed on the similarity and the difference of MIF in both diseases." (PMID 24667663, 2014). "MIF may directly bind to HVEM, and up-regulated HVEM following activation of NF-κB signaling to promote Th17 cell differentiation in patients of Hashimoto’s thyroiditis." (PMID 40169556, 2025). "On the other hand, when thinking the implications of these genetic findings to patients with Hashimoto's thyroiditis, another thyroid autoimmune disease, yet no related evidence has been reported, although the production of MIF is detectable in both diseases." (PMID 24667663, 2014).
influenza (7 papers, 2010 to 2025). An acute viral infection of the respiratory tract, occurring in isolated cases, in epidemics, or in pandemics; it is caused by serologically different strains of viruses (influenzaviruses) designated A, B, and C, has a 3-day incubation period, and usually lasts for 3 to 10 days. "For instance, proinflammatory cytokines like TNF-α and macrophage migration inhibitory factor (MIF) are elevated on the day after influenza vaccination, correlating with these minor symptoms." (PMID 40640868, 2025). "Collectively these studies reveal that during experimental influenza infection elevated MIF levels contributed to both inflammation as well as viral load." (PMID 35464430, 2022). "Consequently, targeting MIF could be therapeutically beneficial in the treatment of influenza infections." (PMID 35464430, 2022).